YTHDF1 (YTH N6-methyladenosine RNA binding protein F1)
Diseases named in the same sentence as YTHDF1 in open-access papers (continued):
Sharing a sentence is not in itself a finding about the gene and the disease.
tumor (continued). "Therefore, the absence of YTHDF1 results in enhanced crosspresentation of tumour antigens; YTHDF1 also promotes crosspriming between CD8+ T cells and antigen-presenting cells (APCs), and this process relies mainly on DCs." (PMID 32411802, 2020). "Furthermore, YTHDF1 silence can increase MHCII expression and interleukin-12 (IL-12) secretion, promoting the infiltration of CD4+ and CD8+ T cells and mediating overexpression of IFN-γ receptor 1 as well as JAK/STAT1 signaling pathway, thus recovering sensitivity to anti-tumor immunity in GC." (PMID 40958857, 2025). "A number of reports have suggested that YTHDF1 plays a functional role in cancer stemness and chemoresistance; however, these studies are based on cancer cell lines, thus lacking the in vivo context of an evolving tumor comprising a mixed stem cell-like and more differentiated cell populations." (PMID 41423446, 2025). "Similarly, in papillary thyroid cancer, m6A enhances the translation of the tumor suppressor STEAP2 in a YTHDF1-dependent manner, leading to the inactivation of the Hedgehog signaling pathway and the epithelium to mesenchymal transition (EMT), restraining the aggressive tumor phenotype." (PMID 38444581, 2024). "In addition, another investigation has demonstrated the m6A-dependent role of YTHDF1 in regulating the translation efficiency of cyclin-dependent kinase 2 (CDK2), CDK4, and cyclin D1 (CCND1), thereby exerting control of NSCLC cell proliferation and xenograft tumor formation." (PMID 39342406, 2024). "Moreover, we analyzed the frequency of tumor-infiltrating DCs (CD45+F4/80–CD11c+MHC-II+) expressing MHC-I–SIINFEKL and determined that IR treatment resulted in a significant increase in the level of MHC-I–SIINFEKL complexes in DCs from Ythdf1-cKO+IR mice compared with WT+IR mice (P < 0.01)." (PMID 39325547, 2024). "Therefore, YTHDF1 deletion may enhance antitumor immunity by facilitating interactions with DCs, rather than promoting their differentiation and proliferation, supporting a potential role of YTHDF2 as a tumor immunosuppressive factor." (PMID 35794625, 2022). "Additionally, the results of subcutaneous transplantation experiments showed that YTHDF1-overexpression tumors grew faster than negative control tumors and that tumor volume and weight in the YTHDF1-overexpression group were larger than those in the control group." (PMID 36439881, 2022). "Moreover, the study was performed based on TCGA and GEO; we could not illustrate the expression of ALKBH5 and YTHDF1 from the protein level or demonstrate the direct mechanisms of ALKBH5/YTHDF1 in anti-tumor immunity." (PMID 34079761, 2021). "TMA cohort analysis (cohort I, N = 184) further revealed a positive correlation between YTHDF1 and the NOTCH1 protein (χ2 = 14.44; P = 0.006) in tumor tissues but not in paired normal tissues." (PMID 41423446, 2025). "A separate study also demonstrated that mice lacking YTHDF1 exhibit an elevated and more effective CD8+ T-cell response against tumor-specific antigens." (PMID 39759516, 2024). "Studies have revealed the importance of m6A methylation in immune evasion, the absence of the m6A reader YTHDF1 in dendritic cells within the TME improves CD8 + T cell cross-priming and tumor antigen presentation." (PMID 38898486, 2024). "Expression levels of YTHDF1 and IGF2BP2 were also compared between tumor tissue and normal tissue, and we found that both of them were higher expressed in tumor tissue." (PMID 35646049, 2022). "YTHDF1 and ZC3H13 were also enriched in nontumor cells, but the percentage of cells with gene expression and the average fold-changes were higher in tumor cells than in nontumor cells." (PMID 35794212, 2022). "The lack of YTHDF1 increases the presentation of tumor antigens and the activation of CD8+ T cells, which are required for containing tumor infiltration." (PMID 36012237, 2022).
tumor (continued). "Fifth, our study only confirmed the relationship between YTHDF1, YTHDF2, CD4, CD8, and FOXP3, however did not reveal which pathway YTHDF1, YTHDF2 affects on the tumor immune profile." (PMID 36479088, 2022). "To further confirm the in situ expression and clinicopathological features of YTHDF1 in patients with HCC, we analyzed a HCC tissue microarray containing 90 tumorous tissues and adjacent nontumorous tissues." (PMID 34088349, 2021). "TRMT61A, TRMT61B, YTHDF1 and YTHDF3 mRNAs were higher in tumor tissues, but protein expression was weaker or not apparently distinct between tumor and normal samples." (PMID 34777359, 2021). "The absence of YTHDF1 in DC can enhance the cross-presentation of tumor antigens and the cross-priming of CD8+ T cells, thereby increasing the anti-tumor response of CD8+ T cells and enhancing the therapeutic effect of PD-L1 checkpoint blockade." (PMID 34616403, 2021). "Differential expression analysis indicated that the protein expression levels of KIAA1429, RBM15, HNRNPC, HNRNPA2B1, YTHDF1, YTHDF2, and YTHDC1 were higher in tumor samples than in non-tumor samples." (PMID 32582536, 2020). "In melanoma, knockdown of METTL3 in bone marrow cells results in the lack of m6A modification on SPRED2, which in turn disrupts YTHDF1-mediated mRNA translation, leading to enhanced activation of NF-κB and STAT3 via the ERK pathway, contributing to tumor progression." (PMID 36830614, 2023). "Nevertheless, it should be noted that our findings did not analyze the signaling between tumor and TME that may regulate the expression of YTHDF1, which require further exploration in vitro or in vivo." (PMID 36650153, 2023).
cancer (215 papers, 2018 to 2026). A tumor composed of atypical neoplastic, often pleomorphic cells that invade other tissues. "Due to its high sensitivity and specificity, YTHDF1 is poised to become a valuable diagnostic marker for pan-cancer applications, with its expression level closely associated with patient prognosis." (PMID 41446042, 2025). "We found that loss of Ythdf1 in DCs enhanced the antitumor effects of ionizing radiation (IR) by increasing the cross-priming capacity of DCs across multiple murine cancer models." (PMID 39325547, 2024). "Recent studies have shown a strong correlation between hypoxia and YTHDF1, and clinical evidence proves that YTHDF1 is associated with cancer progression and can maintain hypoxia tolerance by promoting the translation of certain proteins." (PMID 36675257, 2023). "Here, we reviewed the clinical diagnostic and prognostic values of YTHDF1, as well as the molecular mechanisms of YTHDF1 in progression and metastasis of human cancers." (PMID 36707507, 2023). "YTHDF1 was closely associated with poor prognosis and also used as a molecular marker for clinical diagnosis or therapy in human cancers." (PMID 36707507, 2023). "Diagnostic value of YTHDF1 expression in pan-cancer and corresponding paratumor tissue was evaluated by ROC curve." (PMID 36707507, 2023). "YTHDF1 is also associated with the induction of cancer stemness in conjunction with m6A modification to contribute chemoresistance." (PMID 35884552, 2022). "Recent studies have linked the dysregulation of YTHDF1 to the nervous system, cancer, phase separation, the immune system, and many other biological processes 31-33." (PMID 33456585, 2021). "Recently, YTHDF1 has been reported to be associated with the occurrence and development of several cancers." (PMID 33816306, 2021). "YTHDF1 promotes translation efficiency of m6A-modified mRNAs and is associated with a variety of cancers." (PMID 34677810, 2021). "YTHDF1 deficient mice had enhanced therapeutic efficacy of PD-1 checkpoint blockade which suggested YTHDF1's potential in anti-cancer immunotherapy." (PMID 33732286, 2021). "Only one study has been conducted so far, regarding the epidemiology assessment of YTHDF1 gene SNPs and cancer risk." (PMID 32742460, 2020). "Among these readers, YTHDF1 has been widely implicated in cancer." (PMID 41472023, 2025). "YTHDF1 overexpression downregulated the pathways associated with cancer immunity, including “Allograft rejection” from the hallmark gene set, “Natural killer mediated cytotoxicity” from the KEGG gene set, and “Positive regulation of NF‐kappa B signaling” from the GO gene set." (PMID 39587835, 2025). "Higher expression of YTHDF1 in cancer is associated with poorer survival." (PMID 39821576, 2025). "The RNA N6-methyladenosine (m6A) reader YTHDF1 is implicated in cancer etiology and progression." (PMID 39325547, 2024). "Additionally, YTHDF1 mutations normally affected the amplification in human cancers and contributed to the tumorigenesis of various human cancers." (PMID 36707507, 2023). "All the results revealed that the YTHDF1 had a relatively high accuracy and may be possible used as a diagnostic biomarker for various human cancers." (PMID 36707507, 2023). "Taking YTHDF1 for example, it seems a risk factor in almost all cancers, compared with para-cancer." (PMID 37833468, 2023). "However, a recent study by Li has reported the latest findings on the association between YTHDF1 and cancer-associated fibroblasts (CAFs) in LC." (PMID 38202722, 2023). "However, some researchers thought in hypoxic solid tumors, high level of YTHDF1 was associated with better clinical outcome, and knockdown of YTHDF1 induced the cancer cells resistant to cisplatin." (PMID 36707507, 2023). "In summary, YTHDF1 plays a critical role in both human physiological system development and human cancer progression, and it may serve as a promising diagnostic/prognostic biomarker and a potential therapeutic target." (PMID 36650570, 2023).
cancer (continued). "Epidemiology reports of YTHDF1 gene SNPs and cancer risk are limited." (PMID 34151473, 2021). "Moreover, YTHDF1 up-regulation exhibited a significant association with cancer-related pathways such as cell cycle, pathways in cancer and Wnt signaling pathway." (PMID 34434939, 2021). "The results showed that YTHDF1 expression was significantly different in different immune subtypes and molecular subtypes in most cancer types, which might prove that YTHDF1 is a promising diagnostic pan-cancer biomarker and participates in immune regulation." (PMID 34026603, 2021). "GSEA results showed that high YTHDF1 expression was associated with cancer-related pathways." (PMID 34434939, 2021). "Prior studies have found YTHDF1 to be associated with cancer." (PMID 34151473, 2021). "Furthermore, it is unclear whether genetic or pharmacological interventions targeting YTHDF1 could overcome YTHDF1-associated cancer stemness and chemoresistance." (PMID 41423446, 2025). "However, few studies have been conducted regarding YTHDF1 gene polymorphisms and cancer risk." (PMID 33758623, 2021). "In addition, we speculated that hsa‐miR‐346 is a potential key upstream negative regulator of YTHDF1 that may be associated with cancer treatment." (PMID 32449290, 2020). "We reveal that EZH2 maintains a hyper-m6A state in cancer cells by activating a YTHDF1-mediated m6A autoregulation pathway." (PMID 41252201, 2026). "The robust phenotypes in Ythdf1cki mice and Ythdf1cko, in modulating tumorigenesis, whilst having no apparent effects on normal colon functionality, offer compelling functional evidence of the cancer stemness-modulating role of YTHDF1 in CRC." (PMID 41423446, 2025). "Integrative multiomic profiling demonstrated that NOTCH1 is a critical downstream target of YTHDF1 that promotes cancer stemness and chemoresistance." (PMID 41423446, 2025). "Three m1A regulators (TRMT10C, TRMT6, YTHDF1) were significantly overexpressed in cancer tissues (p < 0.01)." (PMID 41244907, 2025). "YTHDF1 is known to enhance translation and stability of oncogenic transcripts in several cancers, including liver, breast, ovarian, colorectal, and hematologic malignancies." (PMID 41472023, 2025). "Overall, these data suggest the involvement of YTHDF1 in modulating cancer immunity through the inhibition of the IFN‐γ response." (PMID 39587835, 2025). "High YTHDF1 expression is associated with poorer overall survival and reduced cancer immunity, particularly affecting the IFN‐γ response of cancer cells." (PMID 39587835, 2025). "We also confirmed that YTHDF1 promoted CD133 and LGR5 expression in CSCs, xenograft models, and CSC-specific Ythdf1 knock-in/knockout mice, suggesting that YTHDF1 directly boosts cancer stemness properties." (PMID 41423446, 2025). "Recently, curcumin has been shown to affect RNA methylation (m6A) by regulating writer (METTL3/METTL14), eraser (ALKBH5/FTO), and reader (YTHDF1/2) proteins, thereby altering mRNA stability and translation in cancer, inflammatory, and metabolic contexts." (PMID 41322307, 2025). "It is consistent that YTHDF1 is always highly expressed and plays oncogenic roles by enhancing translation in m6A manners in multiple different types of cancers." (PMID 40734692, 2025). "The m6A‐binding protein YTH N6‐methyladenosine RNA‐binding protein F1 (YTHDF1) is overexpressed in GC tissues, correlating with the suppression of cancer immunity and poorer survival rates." (PMID 39587835, 2025). "YTHDF1, a key m6A reader, acts as an oncogenic driver in multiple cancers by modulating mRNA translation and stability, but its role in NPC, especially its mechanism of regulating critical oncogenes like c-MYC, remains poorly defined." (PMID 41167308, 2025). "Here, we report both clinical and preclinical findings: YTHDF1 elevation in DCs after RT was associated with unfavorable outcomes in patients, and IR-induced YTHDF1 in DCs impaired the antitumor immunity elicited by IR in multiple murine cancer models." (PMID 39325547, 2024).
cancer (continued). "YTH domain family protein 1 (YTHDF1) is an example of an m6A’ reader’ that enhances the translation efficacy of m6A-modified mRNAs and plays as an oncogene in human cancers." (PMID 39136000, 2024). "Another gene, YTHDF1, has higher expression in males than in females in some cancers, while this trend is the opposite for a few other cancers." (PMID 39457524, 2024). "YTHDF1 overexpression significantly increased cancer cell proliferation when compared to Vector control group (p < 0.0001), while its knockdown decreased the proliferation of NOZ and GBC‐SD cells (p < 0.0001)." (PMID 38683130, 2024). "DC vaccines with YTHDF1 deletion/inhibition improve the response to RT and immunotherapy in murine cancers." (PMID 39325547, 2024). "In cancer tissues, both YTHDF1 (p < 0.05) and YTHDF2 (p < 0.001) show significant upregulation compared to para‐cancerous tissues, with YTHDF1 exhibiting a more pronounced increase in fold changes (Log2FC = 1.31 vs. 0.98)." (PMID 38683130, 2024). "YTHDF1 promotes migration, invasion, and osteoblast adhesion and induces osteoclast differentiation of cancer cells in vitro and in vivo by inducing EZH2 and CDH11 translation." (PMID 39185313, 2024). "YTHDF1 as an important m6A reader plays critical roles in different types of human cancers, which are involved in regulating DNA damage repair, proliferation, metastasis, immunity and chemoresistance 58-60." (PMID 39309428, 2024). "YTHDF1 is a cancer driving factor that can drive tumorigenicity and metastasis by promoting glycolysis." (PMID 39060874, 2024). "Given the overexpression of YTHDF1 in TAMs and its role in cancer progression, downregulating YTHDF1 in TAMs is expected to reduce M2-type macrophage formation, reshaping the TME for potent antitumor effects." (PMID 38898486, 2024). "In EC, FTO, along with YTHDF1 upregulates the expression of 17beta‐hydroxysteroid dehydrogenase 11 (HSD17B11), thereby promoting the formation of lipid droplets in EC cells and cancer development, which is associated with a poor prognosis for patients with EC." (PMID 38721006, 2024). "Ythdf1-cKO and Ythdf1fl/fl (WT) mice were used to evaluate the antitumor effects of DC-specific Ythdf1 deletion in murine cancer models." (PMID 39325547, 2024). "Our subsequent assays confirmed that overexpression of FTH can sufficiently rescue the inhibitory effect of YTHDF1 silencing in cancer cell proliferation, migration and invasion, then leads to an adverse prognosis." (PMID 37259333, 2023). "Next, we found that the overall survival (OS) and cancer-specific survival rates were poor in BLCA patients with a high expression of YTHDF1 in GSE13507." (PMID 37108067, 2023). "DNA copy number gain of YTHDF1 is a frequent event in CRC and YTHDF1 overexpression was closely correlated to metastasis in cancer patients." (PMID 36707507, 2023). "Some small activators as well as inhibitors of METTL3, FTO, and YTHDF1–3 were designed to treat different cancers both in vitro and in mouse models." (PMID 36795489, 2023). "Recently, enourmous studies have found that YT521-B homology domain family protein 1 (YTHDF1), as an m6A-binding protein, plays a key function in tumorigenesis of cancer." (PMID 36707507, 2023). "Recent studies have shown that YTHDF1 is involved in the occurrence and development of various cancers." (PMID 36733344, 2023). "The oncogenic function of YTHDF1 is progressively being elucidated in several cancers, whereas the development of efficient inhibitors remains stagnant." (PMID 36650153, 2023). "Our findings also indicate that YTHDF1 plays a crucial role in the occurrence and progression of cancer." (PMID 38202722, 2023). "Accumulating evidence confirmed that YTHDF1 dysregulation correlated with radioresistance and poor clinical outcomes in patients with cancers." (PMID 36650570, 2023).